MMP9 (matrix metallopeptidase 9)
Diseases named in the same sentence as MMP9 in open-access papers (continued):
Sharing a sentence is not in itself a finding about the gene and the disease.
aneurysm (continued). "The amount of MMP-9 was found to be increased in abdominal aortic aneurysm (AAA) of small–medium size (up to 6.9 cm) but not in larger aneurysms." (PMID 33573220, 2021). "Interestingly, aneurysms with more pronounced MMP‐2 and MMP‐9 expression show more extensive ECM remodelling and decreased compliance." (PMID 33847905, 2021). "In our previous study, we observed colocalization of gelatinase activity with MMP9 signal in mice without aneurysms." (PMID 33467682, 2021). "In conclusion, MMP-2, MMP-9, and NGAL levels seem to play a major role in the development of aneurysms, and their levels are modulated by statin treatment, suggesting that HMG-CoA reductase inhibitors have a role in the prevention of these clinical manifestations." (PMID 32111073, 2020). "Additionally, more OLCs from aneurysms express HIF-1α, and produce more MMP-9 and cathepsin K, than myeloid cells from the same tissue." (PMID 31546645, 2019). "As an abundant source of MMP-9, impaired macrophage function could prove vital in determining levels of MMP-9 release and therefore aneurysm growth." (PMID 31390798, 2019). "MMP9-/- and MMP2-/- mice were used to determine their effect on aneurysm formation." (PMID 31390798, 2019). "Our previous study revealed that the inhibition of JNK could suppress the production of MMP-2 and MMP-9 in vitro; however, the relationship between JNK and MMPs in the nicotine-related aneurysm model remained unclear." (PMID 27688602, 2016). "We did not detect increase in MMP2 or MMP9 activity in total aneurysm medial tissue samples, whereas MMP-9 activity was significantly increased in SMCs and SMC culture media from aneurysm patients with both BAV and TAV." (PMID 26904289, 2016). "We found only a significantly lower mRNA expression of MMP-2 in aneurysms, whereas higher expression of MMP-9 in aneurysms was not significant between the groups as well as the expression of MMP-1 and MMP-14." (PMID 26539497, 2015). "This work implicates interaction of MMP-9 and MMP-1 with aneurysm formation in Kawasaki disease." (PMID 25191698, 2014). "Significant increase of LDL, cholesterol, triglycerides and circulating inflammatory cells was observed in the Ang II-treated animals, and gene expression studies showed that ICAM-1, VCAM-1, MCP-1, M-CSF, MMP-2, MMP-9 and MMP-12 were upregulated in the aorta of aneurysm-induced mice." (PMID 23826202, 2013). "Increased levels of MMP-2, MMP-3, MMP-9 and MMP-12 have been identified in aneurysm vessel walls." (PMID 15482602, 2004). "Additionally, clodronate liposomes did not lead to a decrease in the levels of MMP2 and MMP9 in the aneurysm walls." (PMID 39595942, 2024). "In our study, nicotine treatment reduced aneurysmal MMP9 activity, although there was no obvious effect on elastin integrity, nor were there any differences in MMP9-positive cells in the aneurysm wall, even though nicotine treatment led to the development of larger AAAs." (PMID 37239088, 2023). "Another aspect of how NGAL could be involved in aneurysm development is that it has been proven that c-Jun N-terminal-kinase is an important molecule in the pathophysiology of AAA, which upregulates both, NGAL and MMP-9." (PMID 34572424, 2021). "The increase was independent of MMP9 level, although in Nrf2 tKO mice without aneurysms, MMP9 signal could colocalise with gelatinase activity, suggesting a role of MMP9 in aortic wall degradation." (PMID 32617140, 2020). "Interestingly, infusion of wild type macrophages resulted in reconstitution of aneurysms in MMP9-/- mice, but not MMP2-/-, highlighting MMP-9 specific release from macrophages, as expected." (PMID 31390798, 2019). "In this study, we aimed to determine the reliability of MMP-9 measurements in patients with acute SAH and patients without SAH but with incidental aneurysms, and also we investigated whether MMP-9 levels were related to SAH severity or VS occurrence and aneurysms." (PMID 27504251, 2016).
aneurysm (continued). "However, we did not detect differences in the distribution of MMP-9 in the aneurysm wall." (PMID 36186984, 2022). "Interestingly, early reports stated that the amount of infiltrated inflammatory cells positively correlates with the size of the aneurysm and an increased expression and activity of MMP-2 and MMP-9 may contribute to rapid AAA growth and rupture of larger aneurysms." (PMID 34572424, 2021). "Aneurysm tissue exposure to different concentrations of DL-Hcy did not induce any significant changes in MMP-9 activity and PAI-1 concentration in comparison to control aneurysm tissue." (PMID 30643799, 2018). "Therefore we speculated that the increase of gelatinase activity in this experimental aneurysm was mainly MMP-2, rather than MMP-9, and MMP-2 might play a more important role than MMP-9 in aneurysm formation." (PMID 25243605, 2014).
pulmonary fibrosis (141 papers, 2005 to 2026). Chronic progressive interstitial lung disorder characterized by the replacement of the lung tissue by connective tissue, leading to progressive dyspnea, respiratory failure, or right heart failure. "These neutrophils release matrix metalloproteinase-9 (MMP-9), a protease linked to extensive tissue remodeling and lung fibrosis." (PMID 41176818, 2025). "For example, a study pointed out that high levels of MMP9 and prothrombotic state are associated with pulmonary fibrosis, a sequela of COVID-19 which affect daily activities." (PMID 35890093, 2022). "The association between the pro-fibrotic mediator MMP-9 and persistent CT-findings highlights the need for more knowledge about the development of pulmonary fibrosis following hospitalisation for COVID-19." (PMID 34853380, 2021). "It was noteworthy that several associated genes (such as TGF‐β, MMP9 and Wnt6) were up‐regulated in pulmonary fibrosis model, which coincided with previous studies." (PMID 32548952, 2020). "MMP-9 is thought to be implicated in fibrotic diseases, such as pulmonary fibrosis, and skin fibrosis in SSc patients." (PMID 30042768, 2018). "Supporting a role in inflammatory disorders that evolve to fibrosis we have demonstrated that MMP8 together with MMP9 associated with neutrophils were increased in hypersensitivity pneumonitis and correlated with the development of lung fibrosis." (PMID 26944412, 2016). "Our in vitro and in vivo experiments showed that silencing β-catenin suppressed the expression of MMP2 and MMP9 at both mRNA and protein levels, which provide a possible mechanism underlying the role of Wnt/β-catenin signaling pathway in lung fibrosis." (PMID 26340635, 2015). "For example, MMP-9-deficient mice exhibit significantly less pulmonary fibrosis in response to bleomycin than their with MMP-9+/+ littermates." (PMID 15642145, 2005). "Moreover, MMP9 in silicosis is associated with the degree of severity and progression lung fibrosis, which is consistent with data from network pharmacology analysis." (PMID 40470053, 2025). "Low extracellular pH caused by enhanced V-ATPase activity could activate MMP-9 and cathepsins to promote the pulmonary fibrosis." (PMID 34991559, 2022). "It has also been suggested that, in pulmonary fibrosis, MMP-9 is linked to inflammatory-induced tissue remodeling, while MMP-2 may be associated with impaired tissue remodeling, leading to abnormal collagen deposition and interstitial fibrosis." (PMID 32429399, 2020). "Enhanced activity of MMP2 or MMP9 is associated with bleomycin-induced pulmonary fibrosis, sustained lung inflammation following endotoxin exposure, interstitial fibrosis following repeated endotoxin exposure, lung injury following exposure to ozone and subacute hyperoxia." (PMID 31842927, 2019). "Of the matrix metalloproteinase members, MMP-9 is implicated in lung fibrosis." (PMID 25945502, 2015). "Similarly, in response to bleomycin, mice deficient in γ-glutamyl transpeptidase showed a reduction in pulmonary fibrosis, in part associated with lower MMP-9 activity in lung tissues." (PMID 15642145, 2005). "Hereby the current study provides an insight on the role of miR-200a in regulating MMP-2 and MMP-9 in bleomycin (BLM)-induced lung fibrosis using both in vitro (A549 cells) and in vivo (C57BL/6 mice) models." (PMID 42004996, 2026). "The results showed that cell infiltration by neutrophils and lymphocytes eased and the severity of pulmonary fibrosis decreased, suggesting that macrophages expressing MMP-9 have anti-inflammation and anti-fibrosis capabilities." (PMID 41596232, 2026). "Previous studies have indicated that metformin inhibits the activity of matrix metalloproteinases, including MMP-9, corroborating our findings that MSC administration also reduced MMP-9 levels and subsequent pulmonary fibrosis." (PMID 40542974, 2025).
pulmonary fibrosis (continued). "Mechanistically, TP-TR downregulated the TLR4/TGF-β level to alleviate airway inflammation and pulmonary fibrosis, concurrently inhibiting MMP9/12 and MUC5AC/5B expression, thereby delaying lung tissue destruction and reducing mucus production." (PMID 40845001, 2025). "In vitro experiments indicated that SM injection alleviated pulmonary fibrosis by downregulating MMP9, IL-6, and TNF-α." (PMID 40630478, 2025). "High levels of MMP-2 and MMP-9 in diseases with lung fibrosis and the progression of fibrosis in mice with MMP-2 deficiency are literature data supporting this idea." (PMID 39860018, 2025). "Our previous study on S protein induction in BALB/c mice showed the remodeling of the extracellular matrix and the role of matrix metalloproteinase-9 (MMP-9) during lung fibrosis." (PMID 39997043, 2025). "Rapamycin alleviates alveolitis and pulmonary fibrosis in the BLM-induced pulmonary fibrosis rat model by reducing the production of matrix metalloproteinase (MMP)-9 and tissue inhibitors of MMP-1 in lung tissue." (PMID 40665395, 2025). "We further examined the expression of MMP-9, which has been reported to correlate with the severity and prognosis of pulmonary fibrosis." (PMID 39513364, 2024). "In patients with ARDS, the excessive production of MMP-9 can destroy the basement membrane, allow fibroblasts to invade the alveolar space, and lead to pulmonary fibrosis." (PMID 39125585, 2024). "In a model of pulmonary fibrosis, neutrophils were found to secrete characteristic NE and MMP-9 and other factors that exacerbate lung inflammation." (PMID 36658472, 2023). "Then, we measured the expression of collagen I, TGF-β1 and the core protein MMP9, markers of pulmonary fibrosis, by Western blotting." (PMID 37781713, 2023). "Elevated MMP-9 expression is a featured characteristic in idiopathic pulmonary fibrosis, and MMP-9 inhibition was reported to ameliorate pulmonary fibrosis in a humanized immuno-deficient mouse model of idiopathic pulmonary fibrosis." (PMID 38235425, 2023). "Yatomi and colleagues provided the first precedent that ATRvD1 ameliorated BLM-induced pulmonary fibrosis in mice by decreasing collagen deposition and cellular accumulation and restoring the matrix metallopeptidase 9 (MMP-9) expression." (PMID 36960058, 2023). "Surprisingly, although MMP-9 levels were increased in the alveolar lavage fluid of idiopathic pulmonary fibrosis patients, MMP-9 promoted abnormal epithelial cell migration and lung tissue repair." (PMID 36387161, 2022). "CAT significantly reduced the MMP2 and MMP9 levels in fibrotic lungs and inhibited the progression of pulmonary fibrosis." (PMID 35685407, 2022). "Based on the observed strong induction of MMP-2 and -9 in both human lung explant tissue of ILD patients and mice with established fibrosis, we determined what effect single MMP-2 or MMP-9 knockout would have on AdTGF-β1 induced lung fibrosis in mice." (PMID 35804363, 2022). "In the clinical study of pulmonary fibrosis, an abnormal MMP-9/TIMP-1 ratio indicates a dysfunctional matrix degradation system, which leads to the progress of pulmonary fibrosis." (PMID 35402615, 2022). "In summary, we evaluated for the first time the roles of MMP-2 and MMP-9 in murine lung fibrosis evoked by adenoviral delivery of biologically active TGF-β1, using both MMP-2 and MMP-9 KO mice as well as MMP-2/-9 double KO mice." (PMID 35804363, 2022). "In experimental pulmonary fibrosis, MMP-9 promotes the release of transforming growth factor-β (TGF-β) and TNF-α, which has been enhanced in rabbits with acute gouty arthritis." (PMID 36297105, 2022). "In this study, the gene expression levels of type I collagen, TGF-β1, α-SMA, Smad-2 and MMP-9 were significantly upregulated in the lung tissue of mice with bleomycin-induced pulmonary fibrosis." (PMID 35625905, 2022). "In the lung fibrosis model of MMP-9-/- mice, deficiency of MMP-9 protected mice from alveolar bronchiolization." (PMID 36387161, 2022).
pulmonary fibrosis (continued). "Based on biochemical along with histopathological examinations and invasive lung function tests in mice, we suggest that MMP-2 and MMP-9 play only a subordinate role in lung fibrosis in mice." (PMID 35804363, 2022). "Together, our data strongly suggest that both gelatinases MMP-2 and MMP-9 play only a subordinate role in experimental lung fibrosis in mice." (PMID 35804363, 2022). "Among the members of the matrix metalloproteinase, MMP-9 is particularly involved in the development of pulmonary fibrosis." (PMID 36552855, 2022). "Neutrophils play a vital role in bleomycin-induced pulmonary fibrosis because neutrophils release profibrotic factors, such as MMP-9 and NE." (PMID 35008524, 2021). "The expression of Metalloproteinase-9 (MMP-9) can significantly impact the development of pulmonary fibrosis." (PMID 35008594, 2021). "The aim of our study was to investigate the role of GSK-3 and its inhibition in the modulation of MMP-9 and -2 in an in vivo mouse model of lung fibrosis and in vitro using different cell lines exposed to pro-inflammatory or pro-fibrotic stimuli." (PMID 34235177, 2021). "Combined with elevated SASP mRNA expression (including Ccl2, Cxcl10, Ccl17, Mmp2, Mmp9, and Mmp12) in sorted macrophages after irradiation, we confirmed that senescent macrophages were partly contributed to lung fibrosis." (PMID 34023858, 2021). "Neutrophils are important for the development of pulmonary fibrosis because they produce various proteases, such as neutrophil elastase (NE) and matrix metalloproteinase-9 (MMP-9), which are important profibrotic factors." (PMID 35008524, 2021). "MMP-2 and MMP-9 are also related to the migration of fibrocytes in idiopathic pulmonary fibrosis, as well as to myofibroblast activation in vascular fibrosis." (PMID 32429399, 2020). "Aside from serine proteases, neutrophils are an important source of matrix metallopeptidases (MMPs), such as MMP-2, MMP-8, and MMP-9, which are involved in pulmonary fibrosis." (PMID 32630825, 2020). "In other words, bleomycin-induced pulmonary fibrosis on 28th day was associated with a significant decrease in MMP-9/TIMP-1 ratio, signifying decrease in MMP-9 activity and increase in TIMP-1 activity." (PMID 32440328, 2020). "For example, lung fibrosis-associated genes (CSF3, IL8, CSF2, IL6, TNF, MMP9, IL1B and PDGFB) were significantly upregulated in SARS-CoV-2-infected NHBE cells." (PMID 32698440, 2020). "MMP-9 is a proteolytic enzyme and its overexpression in macrophages has been shown to attenuate pulmonary fibrosis induced by bleomycin." (PMID 32440328, 2020). "Genetic polymorphism in MMP-9 and TGF-β1 have been found to be associated with pulmonary fibrosis and emphysema in a Chinese population." (PMID 30781876, 2019). "By detecting HGF and MMP-9, we have provided a potential target for ERCs to alleviate lung fibrosis." (PMID 30147727, 2018). "To better understand the effects of BMMCs on lung fibrosis in our model of silicosis, we evaluated mRNA expression of MMP-9 and type III and I procollagen, which are abundant in the early and late phases of lung remodeling." (PMID 29126438, 2017). "Increases in the expression of TIMP-1, an inhibitor of MMP-9, lead to the resolution of pulmonary fibrosis." (PMID 29311918, 2017). "TGF-β1 has been shown to induce the production of MMP9 in several different cell lines, and MMP9 level is elevated in lung fibrosis." (PMID 26753996, 2016). "PQ caused significant pulmonary fibrosis, as indicated by increased BAL concentrations of TGF-β1 and MMP-9." (PMID 26758514, 2016). "Expression levels of miR-21, FSTL1, p-p38MAPK, NF-kB65, p-Smad2/3 and MMP-9 in the lung were increased during PQ-induced pulmonary fibrosis." (PMID 26758514, 2016). "MMP9 has been shown to be involved in the repair of lung tissue following influenza virus infection and can prevent bleomycin-mediated lung fibrosis by remodelling the ECM and degrading cytokines." (PMID 27855162, 2016).